BDNF (brain derived neurotrophic factor)
Diseases named in the same sentence as BDNF in open-access papers (continued):
Sharing a sentence is not in itself a finding about the gene and the disease.
multiple myeloma (19 papers, 2008 to 2025). "For hematological disease, these data are similar in multiple myeloma (MM), which reported that low BDNF levels were associated with poor prognosis." (PMID 40427122, 2025). "BDNF was associated with CIPN in 25 bortezomib-treated multiple myeloma patients evaluated for CIPN using the reduced Total Neuropathy Score (TNS-r) before and during therapy." (PMID 35360655, 2022). "BDNF has been implicated as a novel angiogenic protein in multiple myeloma." (PMID 21767406, 2011). "Similarly in 91 multiple myeloma patients treated with bortezomib or thalidomide lower BDNF levels during treatment were associated with CIPN by Common Terminology Criteria for Adverse Events (CTCAE), and a cut-point of 9.11 ng/ml was 76% sensitive and 71.4% specific to identify CIPN." (PMID 35360655, 2022). "Monocytes demonstrated strikingly similar bivariate correlations between patients with myeloma and AL amyloidosis, with the exception of BDNF as a keystone molecule." (PMID 40977494, 2025). "The mononuclear cells from AL amyloidosis patients had lower expression levels than the cells from myeloma patients for BDNF, calmodulin, phospho‐TBK1, and phospho‐ULK1 in CD4+ T cells and phospho‐GSK3β in monocytes, but higher levels of HO1 in monocytes." (PMID 40977494, 2025). "In patients with multiple myeloma BDNF stimulated bone destruction by promoting osteoclastogenesis, while the inhibition of the BDNF/TrkB axis blocked osteoclastogenesis and bone destruction." (PMID 32927875, 2020). "In patients with multiple myeloma, BDNF was identified as a factor that contributed to osteolytic bone destructions and increased osteoclast formation." (PMID 31242715, 2019). "A previous report documented the involvement of the BDNF/TrkB axis in the induction of OC formation and activation in the context of multiple myeloma, wherein RANKL is overexpressed by OBs, followed by BDNF stimulation." (PMID 27458153, 2016). "Recently, BDNF was identified as a potential osteoclastogenic factor in multiple myeloma, and its serum level correlated positively with that of soluble RANKL." (PMID 23077504, 2012). "The critical roles of BDNF in MM pathophysiology are evidenced by its over-expression in malignant plasma cells and myeloma cell lines, as well as its potential ability to promote the growth of MM cells in vitro." (PMID 23077504, 2012). "Research on multiple myeloma (MM) discovered that human osteoclast precursors expressed BDNF receptor TrkB and a Trk inhibitor, K252a, significantly decreased BDNF-stimulated osteoclast production, suggesting that BDNF utilized TrkB for its influence on osteoclasts." (PMID 36012155, 2022). "Previous studies reported that BDNF is a potential osteoclastogenic factor in multiple myeloma, and myeloma-derived BDNF could promote RANKL secretion and osteoclasts formation." (PMID 34227467, 2021). "Brain-derived neurotrophic factor (BDNF) was recently identified as a factor produced by multiple myeloma (MM) cells, which may contribute to bone resorption and disease progression in MM, though the molecular mechanism of this process is not well understood." (PMID 23077504, 2012). "One explanation for this result is that BDNF is required for the growth of myeloma cells." (PMID 23077504, 2012). "Third, BDNF promotes survival and blocks apoptosis in multiple myeloma cells." (PMID 23077504, 2012). "Taken together, our results demonstrate that myeloma-derived BDNF can promote RANKL secretion by bone marrow stromal cells in the BM milieu through ERK pathway, and that antisense inhibition of endogenous BDNF in MM cells inhibits both osteoclastogenesis and tumor growth in vivo." (PMID 23077504, 2012). "Interestingly, anti-BDNF antibodies in multiple myeloma models produce inhibition of tumour growth and angiogenesis." (PMID 19904265, 2009). "Moreover, BDNF may induce factors produced by marrow stromal cells to enhance the growth and survival of myeloma cells in the marrow." (PMID 23077504, 2012).
multiple myeloma (continued). "Logistic regression and ROC analysis showed that BDNF in CD4+ T cells and heme oxygenase 1 in monocytes significantly distinguished between patients with myeloma versus patients with AL amyloidosis (AUC = 0.75)." (PMID 40977494, 2025). "The expression levels of both BDNF and phospho‐TBK1 were elevated in the CD4+ T cells from AL amyloidosis patients compared to myeloma patients." (PMID 40977494, 2025). "BDNF, calmodulin, and phospho‐TBK1 levels were decreased in CD4+ T cells from AL amyloidosis patients compared to myeloma patients." (PMID 40977494, 2025). "Nevertheless, in contrast to patients with multiple myeloma, in peripheral blood cells of healthy young donors, BDNF application did not increase osteoclast formation in vitro." (PMID 31242715, 2019). "On the other hand, BDNF has been reported to stimulate receptor activator of nuclear factor kappa B ligand (RANKL) production from osteoblasts (OBs), thereby contributing to the formation of osteolytic bone lesions from multiple myeloma." (PMID 27458153, 2016). "In recent years, numerous studies have revealed the important role of BDNF in the pathogenesis of both neuronal and non-neuronal tumors, including multiple myeloma." (PMID 23077504, 2012). "Secondly, we aimed to investigate whether silencing of BDNF in ARH-77 cells with specific short-hairpin RNA (shRNA) blocked in vivo tumorigenesis and osteoclastogenesis and prolonged survival in the SCID-rab model of myeloma bone diseases." (PMID 23077504, 2012). "BDNF and phospho‐TBK1 were significantly correlated in CD4+ T cells from AL amyloidosis patients but not in myeloma patients." (PMID 40977494, 2025). "Additionally, BDNF and phospho‐TBK1 were tightly correlated in the CD4+ T cells from the AL amyloidosis patients but not in the cells from patients with myeloma." (PMID 40977494, 2025).
obsessive-compulsive disorder (19 papers, 2013 to 2025). A disorder characterized by the presence of persistent and recurrent irrational thoughts (obsessions), resulting in marked anxiety and repetitive excessive behaviors (compulsions) as a way to try to decrease that anxiety. "Preclinical studies have shown that levels of BDNF are drastically decreased in the serum and brain tissue of rats with obsessive-compulsive disorder compared to a control group." (PMID 35095581, 2021). "Serum BDNF (log) was inversely associated with PPT (log) (β = -1.01, SE = 0.41), age (β = -0.02, SE = 0.15) and obsessive compulsive disorder (β = -0.36, SE = 0.15), while serum S100B (log) was inversely associated with PPT (log) (β = -1.38, SE = 0.50), only." (PMID 25005881, 2014). "Interestingly, escitalopram increased the serum levels of both GDNF and BDNF in obsessive-compulsive disorder in rats." (PMID 33802323, 2021). "Moreover, a study including 164 proband-parent trios with obsessive-compulsive disorder uncovered significant evidence of an association between OCD and all of the BDNF markers that were tested, including the exact variant found here in this person, p.Val66Met." (PMID 24109560, 2013). "In addition, a meta-analysis showed that compared to those in healthy individuals, peripheral blood BDNF levels in patients with obsessive-compulsive disorder were significantly reduced, indicating that BDNF may serve as a potential biomarker for obsessive-compulsive disorder." (PMID 38707431, 2024). "Variables that were independently correlated with BDNF (log) and S100B (log) significant in the multiple linear regression models included age, log PPT and obsessive compulsive disorder according to the MINI." (PMID 25005881, 2014).
pancreatic cancer (19 papers, 2011 to 2025). "Moreover, we also evaluated the close association between BDNF expression and some critical pancreatic cancer-promoting genes and found that most of these genes were strongly related to BDNF expression in PAAD, including Akt, mTOR, and MAPK." (PMID 34777634, 2021). "In several malignant tumors, including pancreatic cancer, the brain-derived neurotrophic factor (BDNF) functions by binding to the TrkB receptor, subsequently activating the MAP kinase and Akt signaling pathways." (PMID 38567163, 2024). "In pancreatic cancer, BDNF concentrations varied according to the surgical procedure and they fell significantly after tumour resections." (PMID 34395067, 2021). "Our study also revealed that BDNF was positively correlated with chemotherapeutics efficacy and immunosuppressed biomarkers, suggesting that BDNF is an antitumor target in pancreatic cancer." (PMID 34777634, 2021). "We found that multiple cancer types exhibited a significant association between BDNF expression and PFS in the TCGA database, including bladder, colon, kidney, and pancreatic cancers." (PMID 34777634, 2021). "To gain deeper insights into the function of BDNF in the development and progression of pancreatic tumors, we performed correlation analyses to reveal the relevance between BDNF and prooncogenic signaling pathways in PAAD." (PMID 34777634, 2021). "More importantly, activating SMAD2/3 can upregulate the expression of NGF and BDNF in pancreatic cancer cells and promote the PNI of pancreatic cancer in vitro." (PMID 34671554, 2021). "Another intriguing point is the fact that ADRB2 signaling upregulates nerve growth factor (NGF) and brain-derived neurotrophic factor (BDNF) expression in pancreatic cancer, and increased survival was observed in patients treated with nonselective B-blockers." (PMID 32516941, 2020). "The four central pathways, B Cell Receptor, Brain-derived neurotrophic (BDNF), Integrated Pancreatic Cancer and Oncostatin M, have higher frequencies than the rest." (PMID 30120601, 2018). "We found the consistent adverse prognostic value of BDNF expression in PAAD across different databases and BDNF expression in PAAD was positively correlated with tumor T stage, strongly indicating that BDNF served as an unfavorable prognostic biomarker in pancreatic tumors." (PMID 34777634, 2021). "BDNF expression was more upregulated in many cancers compared to normal tissues, including thyroid, ovary, liver, colorectal, gastric, kidney, esophageal, and pancreatic cancers and acute myeloid leukemia." (PMID 34777634, 2021). "In the pancreatic cancer group, BDNF concentrations fell significantly postoperatively (p = 0.011)." (PMID 34395067, 2021). "Taken together with the results of CCLE and TCGA pan-cancer analysis, BDNF was commonly overexpressed in digestive cancers such as esophageal, stomach, colon, and pancreatic cancers, which indicated that BDNF may serve as a potential regulatory mechanism in tumor progression and patient prognosis." (PMID 34777634, 2021). "The results illustrate that Nodal upregulates NGF (nerve growth factor), BDNF (brain-derived neurotrophic factor), and GDNF (glial cell line-derived neurotrophic factor) expression in pancreatic cancer cells and promotes cancer cell migration/invasion." (PMID 35126957, 2022). "Western blot analysis was used to evaluate NGF, BDNF, GDNF, and MMP-9 protein expression in pancreatic cancer cells." (PMID 35126957, 2022). "In fact, ADRB2 is significantly upregulated in these genetically engineered pancreatic cancer mouse models, thereby increasing NGF and BDNF production, stimulating NGF/Trk pathways and enhancing pancreatic nerve density." (PMID 34439102, 2021). "In pancreatic cancer, adrenergic signaling to tumor cells induces the release of NGF and brain-derived neurotrophic factor (BDNF), leading to an increase in nerve density in the tumor region." (PMID 34722510, 2021).
pancreatic cancer (continued). "In pancreatic cancer, adrenergic signaling to tumor cells induces nerve growth factor (NGF) and brain-derived neurotrophic factor (BDNF) release by tumor cells, resulting in increased nerve density in the tumor area." (PMID 33466373, 2021). "After pancreatic cancer lines were treated with different concentrations of HNK, Western blotting was applied to detect the expression of NGF and BDNF." (PMID 34671554, 2021). "Additionally, neurotrophins, including nerve growth factor (NGF), brain-derived neurotrophic factor (BDNF), glial cell line-derived neurotrophic factor (GDNF), and chemokines and neurotransmitters exert various effects in regulating PNI in pancreatic cancer." (PMID 35449152, 2022). "Furthermore, many soluble factors of neurotrophic or axon-guiding nature such as NGF, brain-derived neurotrophic factor (BDNF), neurotrophin 3 (NT-3), glial-cell-derived neurotrophic factor (GDNF), neurturin, artemin, sonic hedgehog, SEMA3D, and others are overexpressed by pancreatic tumour cells." (PMID 35269454, 2022).
prostate carcinoma (19 papers, 2008 to 2025). A carcinoma that arises from epithelial cells of the prostate gland. "Previously, we reported that lower BDNF serum levels were associated with worsening cancer-related fatigue during radiation therapy in prostate cancer patients." (PMID 37462904, 2024). "The elevated expression of TrkB has also been closely related to lymph node metastasis and advanced prostate cancer, indicating that the BDNF/TrkB pathway is crucial for the progression of prostate cancer." (PMID 39648800, 2024). "More recently, the role of BDNF pathway has been investigated in prostate cancer, suggesting the activation of its pathway as a crucial step in disease progression." (PMID 34573332, 2021). "Recently, Li and colleagues investigated the role of BDNF in prostate cancer, demonstrating that the BDNF pathway is crucial for disease progression." (PMID 34573332, 2021). "BDNF is also secreted by prostate cancer cells and has mitogenic effects on the prostatic epithelium." (PMID 32056047, 2020). "Meanwhile, in one study on the molecular mechanisms involved in the progression of prostate cancer, both BDNF and TrkB were found to be overexpressed in prostate cancer tissues and could promote tumor growth." (PMID 39648800, 2024). "During chemotherapy or radiotherapy for prostate cancer, damage to the cavernous nerve, a postganglionic branch of the pelvic ganglion, may lead to ED, and brain-derived neurotrophic factor (BDNF) promotes nerve regeneration by activating the JAK2/STAT pathway in Schwann cells." (PMID 37407943, 2023). "Thus, the BDNF signalling pathway may represent one of the modalities by which resistance exercise inhibits prostate cancer cell growth." (PMID 32056047, 2020). "Other gene variants were also analyzed using such programs such as V66 M variant of human BDNF in psychiatric disorders and computational modeling of complete HOXB13 protein for predicting the functional effect of SNPs and the associated role in hereditary prostate cancer." (PMID 32115674, 2020). "Although the effects of the AR on gene repression are largely unknown, a previous report suggested that the repressor element (RE)-1 silencing transcription factor (REST) mediates the effects of AR on suppression of brain-derived neurotrophic factor (BDNF) in prostate cancer cells." (PMID 27144435, 2016). "BDNF − AS may be a prognosis biomarker and inhibits the proliferation, invasion, migration, and EMT progression molecular intervening target in prostate cancer." (PMID 37370148, 2023).
Borderline personality disorder (18 papers, 2014 to 2025). A personality disorder characterized by impulsive behavior and unpredictable, capricious mood. "Similarly, among individuals with borderline personality disorder, exposure to trauma during childhood was linked with an increase in the methylation of the BDNF gene (implicated in many psychopathologies) into peripheral blood leukocyte cells." (PMID 36231913, 2022). "This can influence neurogenesis throughout the life cycle, as well as showing an association with later pathology; BDNF gene methylation has been associated with completed suicides as well as with development of borderline personality disorder (BPD)." (PMID 29226124, 2017). "Salivary BDNF gene methylation is also a test for borderline personality disorder (BPD) in other neurological disorders." (PMID 39239108, 2024). "In addition, the increase of BDNF through walking can arguably be an antidote to the complexity of the neurophysiological imbalances in mental health cases such as borderline personality disorder." (PMID 40149776, 2025). "The results of the current study are comparable to those reported by a previous study of response to psychological therapy in borderline personality disorder, where responders and nonresponders showed a difference in the direction of change in brain-derived neurotrophic factor DNA methylation." (PMID 25226553, 2014).
chronic kidney disease (18 papers, 2015 to 2025). Impairment of the renal function secondary to chronic kidney damage persisting for three or more months. "The pathophysiology of chronic kidney disease and neuropsychiatric disorders has been commonly associated with mechanisms related to the decreased availability of brain-derived neurotropic factor (BDNF) for renal and neuronal failure." (PMID 33353117, 2020). "Serum from chronic kidney disease (CKD) female and male haemodialysis (HD) patients, and controls, were used to measure BDNF and NSE by enzyme-linked immunosorbent assays, and TMAO by mass spectrometry." (PMID 35292710, 2022). "Compared with an age-matched control group, patients with end-stage renal disease had a significantly lower serum BDNF level due to higher inflammation and oxidative stress after dialysis." (PMID 36782254, 2023). "Chronic kidney disease accompanied by a low serum BDNF concentration is predictive of a significantly high all-cause mortality rate during a median follow-up of 6.0 years among patients with CAD." (PMID 35800175, 2022). "Fourth, although chronic kidney disease is known to be linked to BDNF levels and MACEs, this information was not accessible for the study participants." (PMID 36741831, 2022). "The effects of BDNF on chronic kidney disease require a long-term follow-up study." (PMID 25918454, 2015). "We examined the relationship between brain-derived neurotrophic factor (BDNF) and chronic kidney disease (CKD)." (PMID 36782254, 2023). "In patients with chronic kidney disease, correlation analyses of TMAO with BBB markers brain-derived neurotrophic factor (BDNF) and neuron-specific enolase (NSE) showed significant negative and positive correlations and possible impaired BBB integration." (PMID 39430973, 2024). "We aim to examine BBB disruption, by assessing brain-derived neurotropic factor (BDNF), neuron-specific enolase (NSE) levels, and gut-blood barrier (GBB) disruption by trimethylamine N-oxide (TMAO), in chronic kidney disease (CKD) patients." (PMID 35292710, 2022). "However, it is not known whether plasma BDNF concentration is a predictor of chronic kidney disease (CKD)." (PMID 28575038, 2017).